THRB (thyroid hormone receptor beta)
Diseases named in the same sentence as THRB in open-access papers (continued):
Sharing a sentence is not in itself a finding about the gene and the disease.
tumor (42 papers, 2011 to 2025). "The tumor suppressive action of THRβ has also been supported in clinical literature, with several reports demonstrating favorable outcomes associated with THRβ expression in BC." (PMID 38785457, 2024). "The thyroid hormone receptor beta 1 (TRβ1) is downregulated in several human cancer cell types, which has been associated with development of an aggressive tumor phenotype and the upregulation of Runt-related transcription factor 2 (Runx2)." (PMID 36497320, 2022). "Although an abundance of thyroid hormones is commonly linked to tumor promotion, the nuclear-ligand-dependent receptor THRB is associated with tumor suppression." (PMID 34945824, 2021). "A trend is observed across both tumor and adjacent normal tissue in which decreasing levels of THRB are associated with increasing levels of miRNA-146a." (PMID 32894083, 2020). "This study revealed that higher levels of miR-221, miR-146a, and miR-21 caused a decline in expression of THRB, leading to reduced tumor suppressor role of this gene." (PMID 31307429, 2019). "THRB encodes for thyroid hormone receptor beta (TRβ), which could function as a tumor suppressor." (PMID 23626673, 2013). "Representative protein expression of MEOX2, PHYHIP, RBBP8, ST18, TCF12, and THRB in tumor tissues was demonstrated based on immunohistochemical analysis in the HPA database." (PMID 40869909, 2025). "In vivo, CANA, either alone or in combination with MPA, significantly reduced tumor growth in xenograft models derived from both wild-type and THRB-knockout RL95-2 cells." (PMID 40371351, 2025). "THRβ has been shown to be a well-characterized tumour suppressor in pre-clinical models of various solid tumors." (PMID 38785457, 2024). "The analysis of pan-cancer data from TCGA reveals that THRB is expressed at lower levels in various tumor tissues, including UCEC, compared to normal tissues." (PMID 38383747, 2024). "Subsequently, a necroptosis-related immune gene significantly associated with prognosis (THRB) was identified, western blot and immunohistochemical staining confirmed the differential expression of THRB in normal endometrial tissues and tumor." (PMID 38383747, 2024). "Subsequently, we conducted validation experiments using surgical specimens from UCEC patients treated at our center, and both the IHC and WB (P = 0.007) results demonstrated a decrease in THRB expression levels in tumor tissues." (PMID 38383747, 2024). "Further, in xenograft tumors, the re-expressed THRB inhibited tumor growth and angiogenesis through suppression of vascular endothelial growth factor (VEGF) signaling pathway." (PMID 34761120, 2021). "Previous research has demonstrated that another target gene of miR-21 is thyroid hormone receptor beta (THRB) which is an important tumor suppressor gene." (PMID 26380656, 2015). "Thyroid hormone receptor beta (THRB) gene is commonly deregulated in cancers and, as strengthened by animal models, postulated to play a tumor-suppressive role." (PMID 24849932, 2014). "When FTC-236 cells were treated with demethylation agents such as 5′aza-CdR and zebularine, the expression of the THRB gene was reactivated concurrently with inhibition of cancer cell proliferation, migration, and tumor growth in xenograft models." (PMID 25275301, 2014). "THRB is a known tumor suppressor in TNBC, whose high expression correlates with better survival." (PMID 39171293, 2024). "Evidence suggests that THRβ is a tumor suppressor in various solid tumors." (PMID 38785457, 2024). "In addition, T3 signaling through thyroid hormone receptor beta (TRβ) in the nucleus has a tumor-suppressive effect." (PMID 37158852, 2023). "THRB may act as a tumor suppressor in solid tumors, such as breast, hepatocyte, and thyroid, by inducing apoptosis and reducing the cell renewal capacity to restrain the growth of tumors." (PMID 36293372, 2022). "Other studies highlighted the role of THRβ as a tumor suppressor in BC." (PMID 31947762, 2020).
tumor (continued). "A recent in vitro study suggested a novel role of THRβ, namely THRβ1, in the biology of cancer stem cells that could explain its action as a tumor suppressor in BC." (PMID 31947762, 2020). "In order to check whether tumor-specific changes of miR-155 and miR-425 could affect THRB expression in ccRCC tumors, the expression of both microRNAs was analyzed in 25 ccRCC tissue samples and 25 corresponding non-tumorous kidney samples." (PMID 24849932, 2014). "The expression of THRB was decreased by 56% (p<0.0001) in tumor when compared with control samples." (PMID 24849932, 2014). "Moreover, THRB overexpression potently represses tumor metastasis." (PMID 27934948, 2016). "In view of the critical function of TRβ1 as a tumor suppressor, future studies on the elucidation of how the THRB gene is silenced in cancer cells could provide additional insights for understanding the important role of TRβ1 in cancer development and progression." (PMID 25924236, 2015). "THRβ regulates the activity of the JAK-STAT pathway, ultimately leading to an increase in apoptosis and a reduction in tumor size and proliferation." (PMID 38785457, 2024). "Other proteins were inversely correlated to tumor tissue content, the most significant being; TENX, EHD2, ZA2G, AOC3, FETUA and THRB." (PMID 28445515, 2017). "MEOX2 and PHYHIP, showed no significant protein expression in tumor tissues; the THRB showed “low intensity”, RBBP8 and ST18 showed “medium intensity”, and, interestingly, the TCF12 showed “high intensity”." (PMID 40869909, 2025). "We found that THRB expression was not significantly correlated with tumor purity but showed a positive correlation with immune cell infiltration levels." (PMID 38383747, 2024). "THRB reduces the abundance of VEGF in tumour cells; thus, its abnormal downregulation may lead to enhanced tumour angiogenesis." (PMID 35610231, 2022). "Notably, THRA and THRB mRNA expression were decreased, whereas expression of STMN1 was enhanced, in tumor specimens." (PMID 27934948, 2016). "Furthermore, only half of the studies on THRB methylation was performed on both tumor and paired non-tumorous control tissues." (PMID 24849932, 2014). "In conclusion, these results suggested that although changes in DNMT1 activity may contribute to alterations of THRB expression in cell cultures, the disturbed expression of THRB in ccRCC tissue samples is rather not a result of aberrant, tumor-specific hypermethylation of the gene’s promoter." (PMID 24849932, 2014). "However, THRB CpG methylation analysis performed using BSP, SNaPshot and MSP-PCR consistently revealed no changes in methylation patterns between matched tumor and control samples." (PMID 24849932, 2014).
cancer (30 papers, 2010 to 2025). A tumor composed of atypical neoplastic, often pleomorphic cells that invade other tissues. "Previous studies have demonstrated that loss of heterozygosity, deletion, and reduced expression of the THRB gene are associated with development of diverse human cancers." (PMID 34761120, 2021). "The proteins sodium iodide symporter (NIS), μ-crystallin (CRYM), and thyroid hormone receptor beta (THRB) have been associated with prognosis in various cancer entities." (PMID 34945824, 2021). "Studies have shown that THRA and THRB (another gene that encodes this receptor), may be involved in human cancer." (PMID 33767996, 2021). "Since miR-155 and miR-425 analyzed in our study directly target 3′UTR of THRB and are overexpressed in ccRCC, it is possible that they contribute to decreased THRB expression in this cancer." (PMID 24849932, 2014). "This notion would suggest that reactivation of the THRB gene in cancer cells would lead to attenuation of cancer phenotypes." (PMID 25275301, 2014). "Finally, in addition to the potential for THRβ to serve as a prognostic biomarker and predictive biomarker of response to therapy, the potential re-purposing of THRβ agonists as anti-cancer agents warrants investigation." (PMID 38785457, 2024). "Finally, the potential re-purposing of THRβ agonists as anti-cancer agents warrants investigation." (PMID 38785457, 2024). "Therefore, lower thyroid hormone levels, which may further allow decreased signal to THRβ, might induce cancer-specific RUNX2 overexpression and finally present microcalcification specific to PTC, and mixed calcification, which consists of accumulated and combined microcalcifications." (PMID 30049993, 2018). "While NIS and THRB may serve as possible therapeutic targets, the role of CRYM in cancer is still unclear." (PMID 34945824, 2021). "With the exception of three clusters of NRs representing NR classes I (cluster I: RORC, VDR, PPARA, NR1D1, THRA, RORA, NR1H3; cluster II: RARB, PPARG, THRB) and III (cluster III: ESR1, PGR, AR, ESRRG), NR class was not a good determinate of NR expression patterns in the different cancer types." (PMID 32024906, 2020). "We selected novel epigenetic markers including NKIRAS1/RPL15, THRB RBPS3 (CTDSPL), IQSEC1, NBEAL2, ZIC4, LOC285205, CGGBP1, EPHB1 and FOXP1 that allowed detection of cancer in ovarian biopsies on all stages with sensitivity equal to (72 ± 11)% and specificity (94 ± 5)%." (PMID 23202957, 2012). "Transcriptomics and proteomics as a whole identified key DEPs of the THRB(−/−)/RL95-2 cells, including cellular junctions, metabolism, and cancer-related pathways, suggesting RARβ, CRABP2, and RXRA could be potential targets for MPA resistance and targeted by CANA." (PMID 40371351, 2025).
metabolic disease (3 papers, 2023 to 2025). A congenital disorder (due to inherited enzyme abnormality) or acquired (due to failure of a metabolically important organ) disorder resulting from an abnormal metabolic process. "Given the complementary mechanisms of action of THRβ agonists and GLP-1RAs, their combination represents a highly promising approach for the treatment of metabolic disease, of which MASH is a common comorbidity." (PMID 40500414, 2025).
genetic disease (2 papers, 2020 to 2025). "Resistance to thyroid hormone (RTH) is a rare genetic disorder caused by mutations in the thyroid hormone receptors α or β (THRα, THRβ) genes, leading to impaired tissue responsiveness to thyroid hormones." (PMID 40761432, 2025).
autosomal dominant hereditary disorder (1 paper, 2022). "Resistance to thyroid hormone beta (RTHβ) is an autosomal dominant hereditary disorder that is difficult to diagnose because of its rarity and variable clinical features, which are caused by mutations in the thyroid hormone receptor beta (THRB) gene." (PMID 36531240, 2022).
endocrine disorder (1 paper, 2025). "This case highlights the challenges of diagnosing and managing RTH, a rare endocrine disorder often resulting from mutations in the thyroid hormone receptor-beta (THB) gene." (PMID 40236334, 2025).
THRB also shares sentences with these, for which no sentence is quoted: COVID-19 (3 papers); infection (3); asthma (2); astrocytomas (2); atherosclerosis (2); Cirrhosis (2); congenital hypothyroidism (2); diabetes (2); gastric cancer (2); goiter (2); heart failure (2); lung adenocarcinoma (2); renal cell carcinoma (2); toxic multinodular goiter (2); achromatopsia (1); acromegaly (1); Allergy (1); anti-phospholipid syndrome (1); Anxiety (1); autoimmune hyperthyroidism (1); autoimmune thyroid disease (1); brain cancer (1); cerebral malaria (1); cervical cancer (1); CNS germinoma (1); Cushing syndrome (1); cutaneous melanoma (1); depression (1); edema (1); gestational diabetes mellitus (1).
A further 28 diseases each share a sentence with THRB in 1 paper.